JAK3 (Janus kinase 3)
Diseases named in the same sentence as JAK3 in open-access papers (continued):
Sharing a sentence is not in itself a finding about the gene and the disease.
Eczema (1 paper, 2019). "Though only tested in adults so far, topical JAK1/JAK3 inhibitor tolfacitinib was better than vehicle alone in a phase IIa clinical trial across all endpoints (Eczema Area and Severity Index [EASI], Investigator’s Global Assessment Score [IGA], body surface area and pruritus; p < 0.001)." (PMID 31694234, 2019).
endometrial cancer (1 paper, 2015). Primary or metastatic malignant neoplasm involving the endometrium (mucous membrane that lines the endometrial cavity).
esophageal cancer (1 paper, 2022). A primary or metastatic malignant neoplasm involving the esophagus. "However, Jak3 has not been reported in many studies related to esophageal cancer." (PMID 36430789, 2022).
experimental autoimmune encephalomyelitis (1 paper, 2021). An autoimmune demyelinating disease of the central nervous system that is produced experimentally in animals by the injection of homogenized brain or spinal cord in Freund's adjuvant. "Furthermore, the selective JAK3 inhibitor PF-06651600 demonstrated in vivo treatment efficacy in rodent models of adjuvant-induced arthritis and experimental autoimmune encephalomyelitis, 2 T cell–mediated inflammatory disorders." (PMID 33830087, 2021).
familial chilblain lupus (1 paper, 2020). An instance of Chilblain lupus that is caused by an inherited modification of the individual's genome. "JAK inhibition with tofacitinib (JAK3>JAK1>JAK2), baricitinib (JAK1/2) or ruxolitinib (JAK1/2) showed efficacy for familial chilblain lupus in human case studies and small clinical trials." (PMID 32714331, 2020).
fungal infection (1 paper, 2024). "Consistently, we found that the loss of FcεR1γ significantly impaired the phosphorylation of JAK1 and JAK3 in ILC3s in response to the fungal infection." (PMID 39013884, 2024).
giant cell arteritis (1 paper, 2023). "JAK1 and JAK3 were involved in the chronic inflammation of media and large arteries in an animal model of giant cell arteritis (GCA)." (PMID 37384596, 2023).
glomerulonephritis (1 paper, 2019). A renal disorder characterized by damage in the glomeruli. "Interestingly JAK3-STAT pathway has been claimed to be a responsible pathway in some forms of glomerulonephritis." (PMID 30963011, 2019).
Granuloma (1 paper, 2025). A compact, organized collection of mature mononuclear phagocytes, which may be but is not necessarily accompanied by accessory features such as necrosis. "The concurrent expression of Acetyl-H3K9, Chi3l1, CSF1R, IL4R, TGFß, and Jak3/Stat6 in granulomas of CS further reinforces macrophages towards M2 polarization, thereby leading to anti-inflammatory states and fibrosis." (PMID 40521183, 2025). "Importantly, although previous studies have confirmed the involvement of these receptors in granulomas, our data reveal a novel aspect: the spatial expression pattern shows that activated JAK3/STAT6 signaling largely overlaps with IL4R/IL13R expression but is conspicuously excluded from giant cells." (PMID 40521183, 2025). "Additionally, we observed an enhanced expression of IL13Rα1, Jak3, and STAT6 in macrophages within CS granulomas and the increased phosphorylation of Jak3 and STAT6 are indicative of an activation of anti-inflammatory IL4/IL13 signaling pathways." (PMID 40521183, 2025).
Hyperinsulinemia (1 paper, 2020). An increased concentration of insulin in the blood. "In contrast, loss of JAK3 in mice results in significant body weight increase, associated with impaired glycemic homeostasis, hyperinsulinemia and early symptoms of liver steatosis." (PMID 32413585, 2020).
hyperphosphatemia (1 paper, 2023). Abnormally high level of phosphate in the blood. "Herein, we show that hyperphosphatemia induces the phosphorylation of JAK1 and JAK3 and of the downstream effector STAT1 in HASMCs." (PMID 38254629, 2023).
interstitial lung disease (1 paper, 2023). A diverse group of lung diseases that affect the lung parenchyma. "Tofacitinib, a selective inhibitor of JAK1 and/or JAK3, is considered to alleviate the pulmonary condition of primary Sjögren’s syndrome (pSS)-associated interstitial lung disease (ILD) through its anti-inflammatory and antifibrotic effects." (PMID 38007449, 2023).
ischemia (1 paper, 2017). A hypoperfusion of the BLOOD through an organ or tissue caused by a PATHOLOGIC CONSTRICTION or obstruction of its BLOOD VESSELS, or an absence of BLOOD CIRCULATION. "Immunoblotting data showed that total JAK3 levels are significantly increased in the ipsilateral cerebral cortex in response to focal ischemia, which agrees with previous work identifying an increase in JAK3 mRNA after transient MCAO in rats compared to sham-operated control." (PMID 28790974, 2017).
ischemic stroke (1 paper, 2017). A stroke disorder caused by obstruction of blood flow to the brain, due to thrombotic (local blood clot formation) or embolic (due to a blood clot or other material traveling from another site) event. "We first investigated the effects of ischemic stroke on total and pJAK3/activated JAK3 levels in the cerebral cortex of mice subjected to pMCAO using immunoblotting." (PMID 28790974, 2017). "We are the first to show that total and phosphorylated JAK3 (pJAK3)/activated JAK3 levels are dramatically increased in response to ischemic stroke." (PMID 28790974, 2017). "It has been shown that JAK3 mRNA is upregulated in ischemic stroke, and JAK3 signaling facilitates IL-8-mediated neutrophil chemotaxis." (PMID 28790974, 2017). "In conclusion, the present study shows that JAK3 is expressed on neurons, microglia/macrophages, and endothelial cells in the mouse brain after ischemic stroke." (PMID 28790974, 2017). "We also performed qRT-PCR to more clearly define the role of JAK3 in the inflammatory context of ischemic stroke." (PMID 28790974, 2017). "Associated with pJAK3/activated JAK3, we also determined that phosphorylated STAT3 is markedly increased in the ipsilateral cortex after ischemic stroke, and this is reduced with 10 mg/kg decernotinib." (PMID 28790974, 2017). "In this study, we hypothesized that JAK3 inhibition with decernotinib would reduce infarct size and improve neurological function in a mouse model of ischemic stroke." (PMID 28790974, 2017). "Total and pJAK3/activated JAK3 and phosphorylated STAT3 levels dramatically increase after ischemic stroke in addition to upregulated IL-21 mRNA." (PMID 28790974, 2017). "Overall, our study could not identify JAK3 as a relevant therapeutic target to ameliorate neuroinflammation and reduce brain injury in permanent ischemic stroke." (PMID 28790974, 2017).
keloid (1 paper, 2020). An irregularly shaped, elevated mark on the skin caused by deposits of excessive amounts of collagen during wound healing. "Our data show immune dysregulation, particularly Th2 and JAK3-skewing, along with Th1 and Th17/Th22 expression, in keloid lesions, extending to uninvolved skin, suggesting the potential for systemic therapies targeting these pathways in keloid patients." (PMID 33329590, 2020). "Our results associate keloid tissues with an inflammatory milieu representing multiple T-helper pathways, including the Th2 (e.g. IL-4R, CCL11, TSLP, TNFSF4/OX40L, TNFRSF4/OX40), Th1 (e.g. IFNγ, CXCL10/11), Th17/Th22 (e.g. PI3, CCL20, S100As) axes, as well as the JAK/STAT signaling molecule JAK3." (PMID 33329590, 2020). "Furthermore, keloid lesions displayed significant up-regulation of JAK/STAT signaling molecule, JAK3, as compared to normal skin (FDR<0.05)." (PMID 33329590, 2020).
kidney stone (1 paper, 2021). "Macrophage M1 polarization can facilitate kidney stone formation and promote the differentiation of VSMCs into osteoblastic phenotypes via the Janus kinase 3-signal transducer and activator of transcription protein 3 (JAK3-STAT3) pathway." (PMID 33808324, 2021).
lipodystrophy (1 paper, 2023). A congenital or acquired disorder characterized by abnormal loss or redistribution of the adipose tissue in the body. "ACOX1, ALDOB, protein kinase AMP-activated catalytic subunit alpha 2 (PRKAA2), JAK3, and protein tyrosine phosphatase non-receptor type 11 (PTPN11) have been confirmed to be closely related to β-oxidation of fatty acid, lipogenesis, cholesterol metabolism, and lipodystrophy." (PMID 36397714, 2023).
lymph node metastasis (1 paper, 2020). "Therefore, JAK3/TYK2 level can impact the prognosis of STAD patients with lymph node metastasis." (PMID 33083484, 2020).
Lynch syndrome (1 paper, 2024). An autosomal dominant hereditary neoplastic syndrome characterized by the development of colorectal carcinoma and a high risk of developing endometrial carcinoma, gastric carcinoma, ovarian carcinoma, renal pelvis carcinoma, and small intestinal carcinoma. "In order to elucidate the presence of a JAK3-altered microbiome, we were able to define the microbiome in one APC patient with the seminal JAK3 mutation and one patient with a variant of the Lynch Syndrome, the Muir-Torre Syndrome who did not have a JAK3 mutation." (PMID 39507544, 2024).
meningioma (1 paper, 2024). A generally slow growing tumor attached to the dura mater. "Variants typical for angiomatous (brain) meningioma are PIK3CA, KIT, PTPN11, CDH1, SMAD4, and SMARCB1; the variants typical for psammomatous meningioma are APC, FGFR2, HNF1A, STK11, and JAK3." (PMID 38476782, 2024).
mucinous adenocarcinoma of the appendix (1 paper, 2023). Mucinous adenocarcinoma of the appendix is a very rare, slow growing, well-differentiated epithelial neoplasm of the appendix characterized by abundant mucin production. "In appendiceal cancers, JAK3 gene mutations occur occasionally and are reported in low-grade appendiceal mucinous neoplasms and mucinous adenocarcinomas of the appendix." (PMID 37509254, 2023).
nephritis (1 paper, 2008). Inflammation of renal tissue. "Reflecting the pro-inflammatory functions of nephritis, genes such as JAK3, STAT3 and MAPK1 involved in signalling pathways (JAK/STAT, MAP kinase, antigen presentation, IL1/IL10) are expressed at higher levels in the disease state." (PMID 18980674, 2008). "Increased levels of transcripts for pathway members including JAK3, STAT3, SOCS3, PTPN1, CDKN1A, RRAS and MAPK1 were observed in nephritis." (PMID 18980674, 2008).
neuroendocrine neoplasm (1 paper, 2022). Endocrine tumors, also referred to as neuroendocrine tumors (NETs), are defined by a common phenotype which is characterized by the expression of general markers (neuron specific enolase, chromogranin, synaptophysin) and hormone secretion products. "However, mutations in various genes related to TKs were detected in the tumor samples (JAK3, NRAS, NTRK2, NF1, SETD2) suggesting frequent alteration of TK pathways for neuroendocrine neoplasms." (PMID 36743926, 2022).
NK-cell enteropathy (1 paper, 2020). "Given that 30% frequency of JAK3 K563_C565del mutations were detected in NK cell enteropathy cases, these mutations may potentially be used to differentiate a subset of NK cell enteropathy cases from indolent GI T-LPD cases." (PMID 32850389, 2020).
oral cancer (1 paper, 2023). "JAK-3 gene is a part of an important signalling pathway in oral cancer." (PMID 37720295, 2023).
penile cancer (1 paper, 2024). A primary or metastatic malignant neoplasm that affects the penis. "During lymph node metastasis phase of penile cancer, the expression evolution of JAK-STAT-SOCS1 axis was characterized by the upregulation of JAK3, STAT4 and STAT5B." (PMID 38774752, 2024). "There was a noticeable difference in the expression of JAK3, STAT4 and STAT5A between primary penile cancer and their metastatic lymph nodes." (PMID 38774752, 2024). "During malignant progression phase of penile cancer, the expression evolution of JAK-STAT-SOCS1 axis was characterized by the upregulation of JAK1, JAK3, STAT4, STAT5A and STAT6." (PMID 38774752, 2024).
periodontal diseases (1 paper, 2023). "In contrast, JAK3 inhibition in mice with periodontal disease increased inflammatory infiltrate and bone resorption, indicating a protective role for JAK in the pathogenesis of periodontal diseases." (PMID 37373437, 2023).
Peritoneal Fibrosis (1 paper, 2024). Disorder characterized by a wide range of structural changes in PERITONEUM, resulting from fibrogenic or inflammatory processes. "In summary, DOT1L promoted the expression and activation of tyrosine kinases (EGFR in mesothelial cells and JAK3 in macrophages), promoting cells differentiate into profibrotic phenotype and thus peritoneal fibrosis." (PMID 38172378, 2024). "DOT1L proceeds mesenchymal phenotype differentiation of MCs through upregulating and activating EGFR, and facilitates M2 differentiation of macrophages by upregulating and activating JAK3, subsequently promoting the deposition of ECM and subsequent peritoneal fibrosis." (PMID 38172378, 2024).
Pneumocystis pneumonia (1 paper, 2022). "We report a unique case of JAK3 deficiency with two compound heterozygous JAK3 mutations complicated by disseminated Bacille Calmette–Guérin (BCG) disease and Pneumocystis pneumonia." (PMID 36466884, 2022). "Herein, we describe a unique case of JAK3 deficiency with two compound heterozygous JAK3 mutations complicated by disseminated BCG disease and Pneumocystis jirovecii pneumonia (PJP)." (PMID 36466884, 2022).
polyp (1 paper, 2024). A usually exophytic mass attached to the underlying tissue by a broad base or a thin stalk. "We confirmed the presence of the same JAK3 exon 4 mutation demonstrated via the Ion Torrent run in the four colonic regions and examined and expanded these positive findings to include the transverse colon and rectum and found the mutation in a large polyp with HGD from an additional patient." (PMID 39507544, 2024).
prolactinoma (1 paper, 2022). "Accordingly, JAK3 and CCND1 showed high expression levels in the M6 prolactinoma, indicating the existence of a proliferating autocrine loop in this tumor." (PMID 35978432, 2022). "JAK3, a non-receptor TK intrinsic to the JAK/STAT growth pathway, showed approximately 10-fold overexpression in the M6 prolactinoma and high-grade sarcoma." (PMID 35978432, 2022).
respiratory infections (1 paper, 2022). "Similar to other SCIDs, JAK3 deficiency patients normally present with recurrent severe respiratory infections, refractory diarrhea, thrush, and/or retarded growth, characterized by irrecoverable infections mostly caused by opportunistic and/or multiple pathogens or live-attenuated vaccination." (PMID 36466884, 2022).
Retinal dysplasia (1 paper, 2022). Abnormal growth and differentiation, structure and appearance of the retina present from birth. "Cx3cr1, Mthfr, and Cygb were identified as modifiers of Crb1rd8 retinal dysplasia, Jak3 as an enhancer of a Crb1rd8-dependent neovascular phenotype, and Crb2 as a modifier of retinal dysplasia due to a Crb1 knock-out allele." (PMID 35675330, 2022).
scleroderma (1 paper, 2022). Scleroderma is a rare autoimmune connective tissue disorder characterized by abnormal hardening of the skin and, sometimes, other organs. "Our study indicates that the JAK1 and JAK2 inhibitor has stronger antifibrotic effects than the JAK3 inhibitor, and JAK2 inhibitor use also results in the loss of capillaries in BLM-induced scleroderma mice." (PMID 35733864, 2022). "JAK1 and JAK2 but not JAK3 inhibitors alleviated skin fibrosis in different aspects, such as morphology and dermal thickness, and the JAK2 inhibitor alleviated skin fibrosis the most, demonstrating that JAK inhibition prevented fibrosis in a BLM-induced mouse model of scleroderma." (PMID 35733864, 2022).
sensitization (1 paper, 2014). "SNPs in or near JAK2, CNOT6, MAML1, CD40, IL-4R, and IL-5RA genes were associated with allergic sensitization and SNPs in or near JAK1, JAK3, IL5RA, FCER1A, and ADAM33 genes were associated with cockroach sensitization." (PMID 25505553, 2014).
Sepsis (1 paper, 2024). Sepsis is defined as life-threatening organ dysfunction caused by a dysregulated host response to infection. "In the GSE13904 dataset, the expression trends of BCL2 and FASLG showed a significant decrease in sepsis, while JAK3 exhibited elevation." (PMID 38894720, 2024). "In sepsis, we have identified JAK3 as an apoptosis-related hub gene for sepsis and explored its participation in immune regulation, in order to provide a better picture of the nature of these pathological interactions." (PMID 38894720, 2024). "In summary, we systematically identified 11 apoptosis-related differentially expressed genes in sepsis, and four hub genes (BCL2, FASLG, JAK3 and IRF9) were recognized as valuable diagnostic biomarkers." (PMID 38894720, 2024). "BCL2, FASLG, IRF9 and JAK3 might be key regulatory genes affecting apoptosis in sepsis." (PMID 38894720, 2024). "The volcano plot and heatmap indicated that JAK3, CHMP5 and IFNAR1 were upregulated while CASP8, VDAC2, FASLG, JAK1, STAT4 and BCL2 were downregulated in sepsis." (PMID 38894720, 2024).
Sézary syndrome (1 paper, 2021). "We detected nuclear JAK3 in various CTCL cell lines and primary malignant T cells from patients with Sézary syndrome, a leukemic variant of CTCL." (PMID 33466582, 2021).
small cell lung carcinoma (1 paper, 2020). Small cell lung cancer (SCLC) is a highly aggressive malignant neoplasm, accounting for 10-15% of lung cancer cases, characterized byrapid growth, and early metastasis.
sporotrichosis (1 paper, 2024). The commonest and least serious of the deep mycoses, characterized by nodular lesions of the cutaneous and subcutaneous tissues. "The results showed that the protein expressions of IL-6, JAK3, STAT3, and SOCS3, as well as phosphorylated JAK3 and STAT3, were significantly upregulated, suggesting that the JAK/STAT signaling pathway was activated during the occurrence and development of sporotrichosis." (PMID 38172590, 2024). "The results showed that compared with the control group, the expressions of DKK1 and ACTG2 were significantly downregulated while the expressions of JAK3 and SLC7A11 were significantly upregulated in the tissues of the sporotrichosis patients, consistent with the sequencing data." (PMID 38172590, 2024).
Squamous Cell Carcinomas of the Oropharynx (1 paper, 2022). "In addition, JAK3 mutations were identified in HPV+ Squamous Cell Carcinomas of the Oropharynx (OPSCC) and Cervical Precancers." (PMID 35719936, 2022).
T-LGL leukemia (1 paper, 2017). "A recent clinical investigation has shown the JAK1/JAK3 inhibitor tofacitinib to be a promising salvage therapy for refractory T-LGL leukemia patients with or without STAT3 mutations." (PMID 29228628, 2017).
thyroid cancer (1 paper, 2016). "In addition to well-known BRAF, RAS, and RET mutations, NGS technology facilitated detection of new somatic alterations in thyroid cancer such as MITF, MDM2, JAK3, FLI1, IDH1 etc., all in which the significance of thyroid cancer has not been delineated yet." (PMID 27871285, 2016).
uveitis (1 paper, 2018). An inflammatory process affecting a part of or the entire uvea. "Apart from JAK3, another gene named as JAK1 (ENSP00000343204) was also inferred to be a potential pathogenic uveitis-related gene by our method." (PMID 30349554, 2018).